SCARA3 (scavenger receptor class A member 3)
Description:
Seems to protect cells by scavenging oxidative molecules or harmful products of oxidation.
Synonyms: CSR; CSR1; MSLR1; APC7; MSRL1
Tractability: Antibody: UniProt predicts a signal peptide or a membrane-spanning region. PROTAC: ubiquitination databases record sites on it.
Gene: Protein-coding gene on chromosome 8 (27,633,414 to 27,676,776, forward strand). Ensembl gene ENSG00000168077.
Subcellular location: Endoplasmic reticulum membrane; Golgi apparatus membrane
Subcellular location (Human Protein Atlas): Endoplasmic reticulum
Gene Ontology:
Molecular function: protein binding; scavenger receptor activity
Biological process: response to oxidative stress; UV protection; vesicle-mediated transport
Cellular component: endoplasmic reticulum; endoplasmic reticulum membrane; Golgi membrane
Genetic constraint (gnomAD): Loss-of-function variants: 37 observed, 42.95 expected, observed/expected ratio (o/e) 0.86, 90% interval 0.66 to 1.13. The upper end of that interval is the gene's LOEUF score, 1.13, which puts it in group 4 of 6, group 1 being the genes least tolerant of losing a copy. Missense variants: 692 observed, 746.88 expected, observed/expected ratio (o/e) 0.93, 90% interval 0.87 to 0.99. Synonymous variants: 340 observed, 320.99 expected, observed/expected ratio (o/e) 1.06, 90% interval 0.97 to 1.16.
Homologues: Orthologues: chimpanzee SCARA3 (99% identical), macaque SCARA3 (99% identical), pig SCARA3 (92% identical), guinea pig SCARA3 (91% identical), rat Scara3 (91% identical), mouse Scara3 (91% identical), dog SCARA3 (90% identical), rabbit SCARA3 (78% identical), tropical clawed frog scara3 (62% identical), zebrafish scara3 (46% identical), Caenorhabditis elegans col-187 (15% identical), Caenorhabditis elegans col-184 (14% identical), and 10 more. Paralogues in human: METTL24 (8% identical), CTHRC1 (5% identical).